KRT20 (keratin 20)
Diseases named in the same sentence as KRT20 in open-access papers (continued):
Sharing a sentence is not in itself a finding about the gene and the disease.
lung adenocarcinoma (6 papers, 2006 to 2026). A carcinoma that arises from the lung and is characterized by the presence of malignant glandular epithelial cells. "Right upper lung CT-guided biopsy revealed moderately differentiated adenocarcinoma with immunohistochemical (IHC) staining positive for cytokeratin 7 and thyroid transcription factor and negative for cytokeratin 20, consistent with lung adenocarcinoma." (PMID 39637337, 2024). "Immunohistochemical staining showed that the tumor cells were positive for thyroid transcription factor‐1 (TTF‐1) and keratin 7 (K7) but negative for keratin 20 (K20) and prostate‐specific antigen (Figure not shown), which supported the diagnosis of poorly differentiated lung adenocarcinoma." (PMID 40309045, 2026). "A core biopsy specimen of the left lower lobe mass showed lung adenocarcinoma that was positive for cytokeratin 7 (CK7), negative for cytokeratin 20 (CK20), and positive for thyroid transcription factor 1 on immunoperoxidase staining." (PMID 34398022, 2021). "Immunohistologically, the tumor cells were stained positive for cytokeratin 7 (CK7) in the cytoplasm and for thyroid transcription factor 1 (TTF-1) in the nucleus, but negative for cytokeratin 20 (CK20), suggesting that the tumor cells originated from either thyroid cancer or lung adenocarcinoma." (PMID 18801198, 2008).
skin cancer (6 papers, 2013 to 2025). "On the protein level, immunohistochemical expression of Cytokeratin 20 supports the hypothesis that the Merkel cell is the cellular origin of this aggressive skin tumor." (PMID 23691324, 2013). "Key markers like cytokeratin 20 (CK20) and neuron-specific enolase distinguish MCC from other skin cancers." (PMID 40345052, 2025). "In skin cancer diagnosis, HSD11B1, SLC45A2, and KRT20 have also been demonstrated to play key roles." (PMID 40917881, 2025). "IHC for TBC also shows positivity for CD10, cytokeratin 20, CK 5 and 6, which are negative in other skin cancer cells." (PMID 40406787, 2025).
colorectal adenocarcinoma (5 papers, 2002 to 2022). The most common type of colorectal carcinoma. "Most colorectal adenocarcinomas are cytokeratin 7−/cytokeratin 20+, whereas most ovarian mucinous cancers are cytokeratin 7+/cytokeratin 20+, as seen in our case." (PMID 25821618, 2015). "Out of the 102 samples, in 95% (97 out of 102) of the cases, the cytokeratin 7 and cytokeratin 20 staining pattern characterised and differentiated between lung and colorectal adenocarcinoma." (PMID 12085180, 2002). "Primary and metastatic lung adenocarcinomas show a cytokeratin 7+/cytokeratin 20− staining pattern, while colorectal adenocarcinomas stain cytokeratin 7−/cytokeratin 20+." (PMID 12085180, 2002). "Hematoxylin and eosin (H&E) staining and immunohistochemistry (IHC) analyzes showed that our CCOs mimicked the tissue architecture of their original cancers and retained the expression of colorectal adenocarcinoma markers cytokeratin 20 (CK20) and caudal-type homeobox 2 (CDX2)." (PMID 35990917, 2022). "The isolated cell populations expressed fibroblast activated protein (FAP), but lacked the endothelial marker CD31 and keratin 20 (KRT20), a marker of colorectal adenocarcinoma cells, which demonstrates their stromal origin and activated status." (PMID 31554208, 2019).
ovarian carcinoma (5 papers, 1997 to 2025). A malignant neoplasm originating from the surface ovarian epithelium. "Additionally, primary ovarian carcinomas may exhibit variable positivity for keratin 20, CEA, and CDX2." (PMID 41517393, 2025). "For instance, they have been utilized in the differentiation of mCRC (metastatic colorectal carcinoma), which is KRT20-positive and KRT7-negative, from primary ovarian carcinoma, which is KRT20-negative and KRT7-positive." (PMID 38260844, 2023). "Ovarian cancer cells are KRT7+/KRT20−, whereas prostate cancer cells are negative for both KRT7 and KRT20." (PMID 35267493, 2022). "Similar to the findings in ovarian cancer, in rare incidences, LGR5-/KRT20+ cells could revert into LGR5+/KRT20+, form colonies and proliferate." (PMID 32194856, 2020).
prostate carcinoma (5 papers, 2009 to 2024). A carcinoma that arises from epithelial cells of the prostate gland. "The LUAD tumors are essentially KRT20-negative, whereas others, like colorectal and prostate carcinomas, are usually KRT20-positive." (PMID 39329988, 2024). "We also found KRT20 is upregulated in EA compared with AA cell lines, although in future, we need further explore its significance in prostate cancer progression." (PMID 37476073, 2023). "Cytokeratin 20 at the RNA level is considered a marker for luminal-like subtypes of cancers, including prostate cancer." (PMID 31888257, 2019). "At the protein level, cytokeratin 20 is not routinely used as a marker for luminal-like subtypes in prostate cancer." (PMID 31888257, 2019).
colonic adenocarcinoma (4 papers, 2010 to 2021). "The sinonasal neoplastic tissue showed marked positivity for carcinoembryonic antigen and expressed cytokeratin 20, which differentiates metastatic colonic adenocarcinoma from primary intestinal-type adenocarcinoma (ITAC)." (PMID 34055557, 2021). "These tumors showed atypical immunohistochemistry as a colonic adenocarcinoma: positive for cytokeratin 7, negative for cytokeratin 20, and negative for β-catenin nuclear accumulation." (PMID 26649222, 2015).
gastric cancer (4 papers, 2014 to 2026). A primary or metastatic malignant neoplasm involving the stomach. "Immunohistochemical analysis of this tissue revealed cytokeratin 7 positivity and cytokeratin 20 negativity, identical to the gastric carcinoma resected 29 years earlier." (PMID 42186636, 2026). "We detectedmessenger RNA levels of cytokeratin 20 in gastric cancer cell lines and in the peripheralblood of 125 patients (85 patients with gastric cancer and 40 patients with benignneoplasm) by fluorescence quantitative real-time polymerase chain reaction both before andafter radical resection." (PMID 30827194, 2019). "The combination of cytokeratin 7 and cytokeratin 20 has been widely employed to distinguish among different types of carcinoma and it may be useful in distinguishing mammary from gastric carcinoma." (PMID 25400965, 2014). "In addition, Krt20 expression has been observed in most colorectal and gastric cancers." (PMID 33604610, 2021).
lung carcinoma (4 papers, 2012 to 2024). "As for the genomics level, variants in KRT20 are associated with lung cancer." (PMID 35155435, 2022). "The previous research suggests that KRT20 may serve as a potential biomarker for diagnosing and monitoring lung cancer to distinguish them from KRT20-positive tumors." (PMID 39329988, 2024). "Thus, the immunostaining for KRT20 in tumors or CTCs could be helpful in early detection and adjustments of personalized treatment strategies for lung cancer patients." (PMID 39329988, 2024). "Several genes, such as HOXC12, HAND1, VIPR2, KRT20, MMP24, and VIPR2, were discovered, and their special roles at different omics levels of lung cancer were confirmed." (PMID 35155435, 2022). "The most useful immunohistochemical stains to differentiate gastrointestinal carcinoma from lung carcinoma are TTF-1, cytokeratin 7, cytokeratin 20, CDX2, and villin." (PMID 23119210, 2012). "The first gene KRT20 (ENSP00000167588) has been shown to define the invasive characteristics of cancer cells at the transcriptomics level in multiple cancer subtypes, including lung cancer." (PMID 35155435, 2022).
neuroendocrine carcinoma (4 papers, 2015 to 2025). A malignant neuroendocrine neoplasm composed of cells containing secretory granules that stain positive for NSE and chromogranin. "Biopsy of a scalp tumor revealed neuroendocrine carcinoma with positive staining for cytokeratin 20 (CK20) and synaptophysin, confirming the diagnosis of MCC." (PMID 31164102, 2019). "Negative results were obtained for cytokeratin 20, CDX2, CD56, S100, and neuroendocrine markers such as synaptophysin, which excluded other tumor types, including neuroendocrine carcinoma and adenocarcinoma." (PMID 39860304, 2025).
pancreatic cancer (4 papers, 2020 to 2024). "We further noticed that some proteins such as PDCD6IP, SERPINA12, KRT20 showed statistically significant population-wise enrichment in pancreatic cancer compared to benign pancreatic diseases." (PMID 36993200, 2024). "KRT20 overexpression is frequently found in pancreatic tumor tissues and correlates with poor prognosis, suggesting a biological basis for their high levels in the cEVs of PDAC patients." (PMID 39693144, 2024). "CNV-positive cells expressed Krt20, a marker of pancreatic cancer cells, and Aim2, which activates caspase 1 to process Il1 and Il18 precursors and regulates inflammasome activation." (PMID 32908137, 2020).
rectal cancer (4 papers, 2015 to 2021). A primary or metastatic malignant neoplasm that affects the rectum. "Immunohistochemical staining showed that the specimen was positive for both cytokeratin 20 (CK20) and caudal-type homeobox 2 (CDX2) and negative for cytokeratin-7 (CK7), which indicated that it had originated from rectal cancer." (PMID 28748455, 2017). "Immunohistochemical staining indicated that both the rectal lesion and anal fistula were cytokeratin 7 (CK7) (−) and cytokeratin 20 (CK20) (+), and the patient’s condition was diagnosed as implantation of rectal cancer in an anal fistula." (PMID 26943447, 2015). "We performed H&E staining and immunostaining of the proteins cytokeratin 7, cytokeratin 20, and caudal type homeobox 2 transcription factor to confirm that our PDTOs originated from rectal cancer tissue and not from normal rectal mucosa." (PMID 34359661, 2021).
small cell lung carcinoma (4 papers, 2011 to 2025). Small cell lung cancer (SCLC) is a highly aggressive malignant neoplasm, accounting for 10-15% of lung cancer cases, characterized byrapid growth, and early metastasis. "In particular, KRT20 was used as a marker for differentiating MCC from small cell carcinoma of the lung." (PMID 24634783, 2014). "An immunopanel including cytokeratin 20 (CK20) and thyroid transcription factor-1 (TTF-1) allows the greatest sensitivity and specificity for excluding small cell lung cancer." (PMID 28138393, 2017). "Along with KRT20, NEFM was shown to be effective at discriminating MCC from small cell lung carcinoma with the majority of MCC being positive for both NEFM and KRT20 while NEFM and KRT20 were almost completely absent from small cell lung carcinoma." (PMID 24634783, 2014).
basal cell carcinoma (3 papers, 2014 to 2025). A carcinoma involving the basal cells. "Apart from the two components already mentioned—basaloid epithelial and mesenchymal—these tumors often have a prominent Merkel cell population, which is often used as a diagnostic aid in the differential diagnosis with basal cell carcinoma, by means of focal cytokeratin 20 dot-like positivity." (PMID 41283586, 2025).
colitis (3 papers, 2016 to 2025). Inflammation of the colon. "However, during acute colitis, the abundance of KRT20-expressing cells was increased, with WT mice showing a much greater increase than IFN-γR KO mice." (PMID 40319019, 2025). "Among others, dysregulation of KRT20 expression has been reported in the stomach induced by H. pylori infection, in Barrett’s esophagus related to gastric reflux, and in murine DSS-induced colitis, as well." (PMID 35327321, 2022).
colorectal tumors (3 papers, 2016 to 2025). "Cytokeratin 20 (CK20) is a low molecular weight member of the Cytokeratin family of proteins that is expressed in primary colorectal tumors and their metastases." (PMID 27386436, 2016). "Similar results occur upon ablation of Lgr5Hi cells in human colorectal tumor xenografts, where cells expressing differentiation markers such as keratin 20 (KRT20+) could regenerate the ablated Lgr5Hi tumor cell population." (PMID 30171151, 2018). "Considering the production of the differentiated epithelial cell marker Krt20, it could be concluded that a method mimicking the suppression of Tcf7l2 expression (inhibition of the Wnt pathway) could be a therapeutic approach to the treatment of colorectal tumors." (PMID 40221753, 2025).
gastric adenocarcinoma (3 papers, 2008 to 2026). "In immunohistochemical studies the tumor cells showed a strong expression of cytokeratin 7 and focal expression of cytokeratin 20 consistent with the diagnosis of gastric adenocarcinoma." (PMID 18279511, 2008). "Immunohistochemical analysis showed that these cells expressed cytokeratin 7 but not cytokeratin 20, CD117, CD34, chromogranin A, and synaptophysin, confirming the diagnosis of exophytic gastric adenocarcinoma with peritoneal dissemination." (PMID 42017098, 2026).
lymph node metastases (3 papers, 2018 to 2024). "Cytokeratin 20 (CK20) and mitogen-activated protein kinase kinase kinase 8 (MAP3K8) up-regulations were observed in MSS tumors and associated with lymph node metastasis, recurrence, and/or distant metastasis and short median survival." (PMID 38541076, 2024). "Quantitating KRT20 expression by RT-PCR is a very sensitive and accurate method to detect unknown lymph node metastases." (PMID 36949761, 2023).
melanoma (3 papers, 2013 to 2023). A malignant, usually aggressive tumor composed of atypical, neoplastic melanocytes. "The histological features of melanomas imitate those of lymphomas, sarcomas, neuroendocrine tumors, and Merkel cell carcinomas; for instance, both express epithelial cytokeratin 20 and endothelial markers, thus making melanomas a serious challenge, even for an experienced pathologist." (PMID 37504268, 2023).
neuroendocrine tumor (3 papers, 2022 to 2025). "Unlike other neuroendocrine tumors, perinuclear dot-like staining with Cytokeratin 20 (CK20) is MCC’s distinguishing diagnostic hallmark." (PMID 39841326, 2025).
ovarian tumors (3 papers, 2016 to 2024). "Mucinous ovarian tumors of non-teratomatous origin typically exhibit an immunophenotype akin to that of the upper gastrointestinal tract, characterized by the expression of Cytokeratin 7 (CK7)-positive and Cytokeratin 20 (CK20)-positive or -negative." (PMID 39040449, 2024).
thyroid tumor (3 papers, 2011 to 2023). A benign or malignant neoplasm affecting the thyroid gland. "Due to the fact that KRT7 has been positively stained in almost all thyroid neoplasms while KRT20 has consistently been undetectable, KRT7 and KRT20 are excellent candidates for the thyroid cancer sequencing panel." (PMID 28117295, 2017). "While the study found a positive result for KRT7, none of the thyroid tumors or their metastases reacted at all to the KRT20 antibody." (PMID 28117295, 2017). "Almost all thyroidal tumor’s expression levels for KRT7 and KRT20 have been found to be positive and negative, respectively." (PMID 28117295, 2017).
urothelial bladder cancer (3 papers, 2021 to 2023). "Their findings revealed that all instances of transitional cell carcinoma of the bladder displayed KRT7 expression, while 75% tested positive for KRT20." (PMID 38260844, 2023). "NanoString-based gene expression analysis using typically luminal (GATA3+/KRT20+) and basal markers (KRT14+/KRT5+/GATA3low/-/KRT20low/-) classified urothelial bladder carcinoma samples as luminal, basal, and a third category (KRT14-/KRT5-/GATA3-/KRT20-), null/double negative (non-luminal/non-basal)." (PMID 34771663, 2021).
acute kidney injury (2 papers, 2024 to 2025). Sudden and sustained deterioration of the kidney function characterized by decreased glomerular filtration rate, increased serum creatinine or oliguria. "Cytokeratin 20 levels in urine are predictive of the progression of acute kidney injury to chronic kidney disease and may help identify patients at-risk early after injury." (PMID 38805402, 2024).
Ampullary cancer (2 papers, 2010 to 2011). "Ampullary cancer (AC) was classified as pancreatobiliary, intestinal, or other subtype based on the expression of cytokeratin 7 (CK7) and cytokeratin 20 (CK20)." (PMID 21992455, 2011).
carcinoma in situ (2 papers, 2020 to 2023).
cyst (2 papers, 2016 to 2019). A sac-like closed membranous structure that may be empty or contain fluid or amorphous material. "Furthermore, immunohistochemical staining showed the cyst to be cytokeratin 7 (CK7) positive and cytokeratin 20 (CK20) and CDX2 negative." (PMID 26943696, 2016).
medullary carcinomas (2 papers, 2017). "A second retrospective study examined 153 thyroid carcinoma samples for KRT7/KRT20 immunohistochemically, and they found that all papillary carcinomas, follicular carcinomas, and medullary carcinomas were KRT7 positive and KRT20 negative." (PMID 28117295, 2017).
metastatic carcinoma (2 papers, 2016 to 2023). A carcinoma which has spread from the original site of growth to another anatomic site. "We report a rare case of metastatic carcinoma originating from a cecal adenocarcinoma with an unusual cytokeratin 7/cytokeratin 20 immunophenotype." (PMID 26810414, 2016).
non-small cell lung carcinoma (2 papers, 2015 to 2018). A group of at least three distinct histological types of lung cancer, including non-small cell squamous cell carcinoma, adenocarcinoma, and large cell carcinoma. "Tumour cells were negative for cytokeratin 20, gross cystic disease fluid protein 15 and oestrogen receptor, in keeping with metastatic adenocarcinoma, primary non-small cell lung cancer." (PMID 30092841, 2018). "Further, PDX tissue sections generally did not express antigens characteristic of non-small cell lung cancers, including Keratin 5, Keratin 6, Keratin 7, Keratin 14, Keratin 20, TTF1, TP63, and Napsin A." (PMID 25955027, 2015).
small cell carcinoma (2 papers, 2013 to 2024). A neuroendocrine carcinoma composed of small malignant cells which are often said to resemble "oat cells" under the microscope. "Immunostaining further validated the presence of small cell carcinoma, with stains showing the tumor to be positive for pan-keratin, cytokeratin 20 (CK20), synaptophysin, focally positive for chromogranin and thyroid transcription factor 1 (TTF-1), and negative for cytokeratin 7 (CK7) and GATA-3." (PMID 39651006, 2024).
urothelial neoplasm (2 papers, 2013 to 2022). A neoplasm involving a urothelium. "Expression of cytokeratin 20 would hint at a urothelial neoplasm." (PMID 23721502, 2013).
acute graft versus host disease (1 paper, 2022). A syndrome of immunologically mediated tissue damage that may occur following an allogeneic transplant, usually affecting the skin, liver, and GI tract. "Our observations indicate that the concentration of circulating KRT20 may be affected by the development of acute graft versus host disease (which may follow aHSCT)." (PMID 35327321, 2022).
adenopathies (1 paper, 2021). "Tissue biopsies from the primary tumor and right groin adenopathies revealed an adenocarcinoma, with positive cytokeratin-7 (CK7), epithelial membrane antigen (EMA), thyroid transcription factor-1 (TTF-1) immunohistochemistry (IHC), and negative cytokeratin-20 (CK20) staining." (PMID 33608032, 2021).
ampullary adenocarcinoma (1 paper, 2016). "The ampullary adenocarcinoma cell lines MDA-AMP7, AVC1, RCB1280, SNU478 and SNU869 were grown in standard culture medium and expression of KRT7, KRT20, CDX2, E-Cadherin and ZEB1 mRNA was measured by real-time PCR." (PMID 26951071, 2016).
anal adenocarcinomas (1 paper, 2018). "Beside T-cell subsets, epithelial PD-L1 expression was also statistically more important in anal adenocarcinomas arising from the anal glands/transitional zone compared to their Krt20/CDX2-positive counterparts." (PMID 29700411, 2018).